TXNIP (thioredoxin interacting protein)
Diseases named in the same sentence as TXNIP in open-access papers (continued):
Sharing a sentence is not in itself a finding about the gene and the disease.
Wolfram syndrome (1 paper, 2020). Wolfram syndrome (WS) also known as DIDMOAD, is a neurodegenerative disorder characterized by type I diabetes mellitus (DM), diabetes insipidus (DI), sensorineural deafness (D), bilateral optical atrophy (OA) and neurological signs. "A recent study showed that in human pluripotent stem cells, derived insulin-producing β cells (sc-β cells) with or without gene collection of the pathogenic variant of Wolfram Syndrome (WS) revealed a 1.5–2-fold TXNIP gene induction by high glucose stimulation." (PMID 32824669, 2020).
tumor (191 papers, 2005 to 2026). "Spatial transcriptomic analysis further identified region-specific expression patterns and spatially restricted tumor niches, including the regional establishment of TXNIP and BIRC3 as genes associated with metabolic stress and inflammatory survival pathways." (PMID 41972735, 2026). "Our research indicates that BET inhibition led to the induction of TXNIP, which caused cell cycle arrest, offering new insights into the anti-tumor mechanisms of BET inhibitors." (PMID 41249136, 2025). "To elucidate the role of TXNIP on immune reactivity and anti-tumor effector functions of T cells, we generated TXNIP-deficient T cells by CRISPR Cas-9 genome editing." (PMID 40260243, 2025). "The mechanisms underlying the context-dependent nature of tumor cell responses such as that of TXNIP to Dpep have yet to be thoroughly investigated." (PMID 38920655, 2024). "The Ma_2 cluster was found to be enriched in immune-related pathways, like interleukin γ and the complement system, leading to its classification as TXNIP Ma, associated with tumor resistance." (PMID 39136841, 2024). "Previous research has demonstratedthat TXNIP expression is downregulated in a range of tumor tissues, and aberrant TXNIPexpression is linked to a favorable patient prognosis." (PMID 38229544, 2024). "Oncogene-mediated downregulation of TXNIP is mostly associated with inhibition of cell death and an increase in cellular metabolism, which favour tumor proliferative abilities and resistance to anticancer treatment." (PMID 37794178, 2023). "TXNIP is lowly expressed in most cancers, and distinct associations exist between TXNIP expression and the prognosis of tumor patients." (PMID 35843949, 2022). "Consistently, our findings showed that five genes related to the MMR of DNA were positively linked to TXNIP expression in many types of tumor (all P < 0.01)." (PMID 35843949, 2022). "TXNIP expression was associated with tumor mutational burden, microsatellite instability, mismatch repair genes, tumor infiltrating immune cell abundance as well as cancer-associated fibroblasts." (PMID 35843949, 2022). "The Clinical pathology study of our clinical cohort found that the expression of TXNIP was significantly associated with tumor size, tumor nodules, and TNM stage." (PMID 33323975, 2021). "In contrary, we showed a significant correlation between cytoplasmic TXNIP expression, inefficient vascularisation by unorganized and tortuous vessels causing tumour cell necrosis and postoperative tumour relapse of cRCC." (PMID 34433833, 2021). "Univariate Cox regression analysis revealed that tumor size, grade, T classification, necrosis as well as cytoplasmic TXNIP positivity were significantly associated with postoperative tumour progression (all p < 0.001)." (PMID 34433833, 2021). "The shift of TXNIP/TXN balance towards overexpression of TXNIP is associated with proliferation of endothelial cells during tumor angiogenesis." (PMID 34433833, 2021). "Some researchers have found that NaBu-induced TXNIP can interact with TRAF6 through its PPxY motif, which can cause changes in TXNIP expression and its polyubiquitination, which then affect tumor migration and proliferation in NSCLC." (PMID 33194655, 2020). "In spite of these findings, the precise molecular mechanisms behind TXNIP tumor suppressor activity and the functional association between TXNIP and autophagy have remained entirely elusive." (PMID 32511893, 2020). "It was found that the number of Natural Killer (NK) cells is profoundly reduced in TXNIP-WKO, which was linked to poor ability of tumor rejection in TXNIP-WKO." (PMID 32824669, 2020). "It has been well-documented that TXNIP expression is positively associated with the loss of tumor differentiation and that TXNIP levels gradually decrease as tumors advance in animal models." (PMID 33194655, 2020).
tumor (continued). "TXNIP has been implicated as both a tumor suppressor and an oncogene and is critical for regulating the redox status in cells through its interaction with thioredoxin (TRX)." (PMID 30479697, 2018). "Culture of tumor cells with suberoylanilide hydroxamic acid that is an inhibitor of histone deacetylases and an effective inducer of TXNIP expression cause growth suppression and/or apoptosis in these cells." (PMID 24376827, 2013). "High TXNIP expression is associated with favorable outcomes, consistent with its postulated role as a tumor suppressor gene based on its growth-suppressing activity and the increased occurrences of tumors with deficiency of TXNIP." (PMID 20844768, 2010). "In BC, TXNIP expression is closely linked to tumor progression and treatment outcome." (PMID 40136510, 2025). "In cancer, the regulation of TXNIP may be one of the mechanisms underlying proliferation and cancer progression, and TXNIP has a relatively small effect on tumor survival compared to the overall pathway-mediated inhibition of oncogenic drivers." (PMID 38789868, 2024). "However, TXNIP is involved in glucose metabolism and transport, and inhibition of TXNIP induces cell cycle arrest and drives apoptotic events and the consequent potential tumor risk are the main issues in targeting TXNIP applications." (PMID 37530723, 2023). "Finally, to test the effect of TXNIP loss on orthotopic tumor growth in vivo, we transplanted parental 231 and 231:TKO cells into the cleared mammary fat pads of immunocompromised mice and used caliper measurements to monitor their growth over time." (PMID 36930677, 2023). "Since WT1 and IL-24 are rarely expressed in KIRC tissues, we investigated the clinical prognostic significance of WT1-regulated genes, including GDD45A and TXNIP, finding that the levels of these genes were associated with the histological grade, tumor stage, and metastasis in KIRC patients." (PMID 35915803, 2022). "Finally, DORZOLAMIDE has shown antitumor activity which affects TXNIP-dependent tumour suppression pathways and also causes downregulation in the level of bcl-2 in cancer cells." (PMID 35379165, 2022). "We thus hypothesized that TXNIP may activate the tumor-associated macrophages (TAMs) along with shifting macrophage phenotype to a more anti-inflammatory state." (PMID 35843949, 2022). "TXNIP has been hypothesized as a possible tumor suppressor in cancer due to its capacity to cause oxidative stress-mediated apoptosis in cancer cell lines and tumor tissues." (PMID 36366411, 2022). "Thus, decreasing levels of TTP/ZFP36 and TXNIP in malignant clones indicate loss of tumor-suppressive functions." (PMID 34583709, 2021). "However, in multivariate Cox regression analysis only cytoplasmic TXNIP expression and necrosis remained independent predictor of cancer progression indicating two times higher risk of postoperative tumour relapse." (PMID 34433833, 2021). "Therefore, this gene is considered to be a tumour suppressor and high levels of TXNIP expression are associated with a positive prognosis." (PMID 32138149, 2020). "In Cp state, high DE miRNAs such as miRNA-449-A also showed interaction with the hub connectors CCND1 and TXNIP (encoding a thioredoxin-binding protein member of the alpha arrestin protein family that regulates redox signaling, and possibly a tumor suppressor)." (PMID 28824643, 2017). "The inverse association of TXNRD1 and TXNIP with MFI found in this study supports the hypothesis that the maintenance of an active thioredoxin system is advantageous to the tumor cells because it limits oxidative damage and enables them to survive." (PMID 20584310, 2010). "Thus, TXNIP imbalance has been linked to various diseases, including diabetes, ischemia/reperfusion injury, Alzheimer’s disease, and cancer, where it has been proposed as a tumor suppressor and biomarker for cancer progression." (PMID 41213907, 2025).
tumor (continued). "Therefore, TXNIP has been hypothesized as a possible tumor suppressor in cancer due to its capacity to cause oxidative stress-mediated apoptosis in cancer cell lines and tumor tissues." (PMID 36366411, 2022). "TXNIP is involved in cellular oxidation, regulation of glucose metabolism and lipid metabolism, and tumor regulation, acting as an antitumor or protumor agent." (PMID 40149637, 2025). "TXNIP levels in the primary tumor pre-ADT were significantly higher than in relapse samples from the lymph node (p < 0.0001) and abdominal mass (p < 0.01)." (PMID 41213907, 2025). "Consistent with the findings in cultured cancer cells, JQ1 increased TXNIP expression while inhibited protein UFMylation in the tumor xenografts." (PMID 41249136, 2025). "Taken together, these data highlight the role of TXNIP in T cell immune responses and tumor cell killing capacity." (PMID 40260243, 2025). "Nevertheless, the findings obtained from diverse tumor studies utilizing varied methodologies exhibit paradox, suggesting that the role of TXNIP can be variable upon the specific tumor type and stage." (PMID 40182050, 2025). "Analyzing the histopathological samples from PCa patients, we confirmed the decrease of TXNIP protein in tumor tissue compared to the adjacent benign tissue (p < 0.001)." (PMID 41213907, 2025). "scRNA-seq data exhibited that TXNIP is not only expressed in lymphocytes but also in other immune cells, tumor cells and stromal cells, the expression in lymphocytes being the highest." (PMID 40260243, 2025). "Our investigation aimed to uncover the mechanisms behind TXNIP’s tumor-suppressive actions to inform the development of new therapeutic strategies." (PMID 40175348, 2025). "This indicates that the overexpression of NCL leads to the relief of MYC-mediated transcriptional inhibition of TXNIP, thereby promoting tumor growth in vivo." (PMID 40346484, 2025). "Here, we demonstrated that TXNIP knockdown increased MDA-MB-231 tumor growth and metastasis in a mouse model." (PMID 40175348, 2025). "In vivo, NCL inhibited CD8+ T cell glucose metabolism through the MYC/TXNIP axis, hindering anti-tumor immune function." (PMID 40346484, 2025). "In this study, we explored the anticancer effects of COR on HCC cells and demonstrated for the first time that COR can mediate tumor cell pyroptosis through the upregulation of TXNIP under ERS." (PMID 40008893, 2025). "TXNIP plays a major role in regulating cellular reduction–oxidation reactions and acts as a tumor suppressor in multiple malignancies." (PMID 39751954, 2025). "The results indicated that TOB1‐AS1 overexpression decreased miR‐27a‐3p expression and increased TXNIP expression in tumor tissues of tumor‐bearing mice and inhibited tumor growth in vivo." (PMID 40665897, 2025). "TXNIP is involved in essential cellular processes such as energy metabolism, cell proliferation, and differentiation, and is widely recognized as a tumor suppressor that is frequently downregulated in a variety of cancers." (PMID 40665897, 2025). "To determine the effect of TXNIP on tumor growth, we injected TXNIP-KD MDA-MB-231 cells, TXNIP-OE HCC-1954 cells, or the WT parental cell lines into the mammary fat pads of NSG mice." (PMID 40175348, 2025). "This enzyme is critical for scavenging lipid peroxides, preventing ferroptosis in tumor cells, and TXNIP has recently been regarded as a pro-ferroptotic protein." (PMID 41213907, 2025). "Coherently, TXNIP overexpression has been found to decrease chemoresistance by increasing drug‐induced ROS and DNA damage levels in tumor cells." (PMID 39364720, 2025). "Emerging evidence also supports a role as a tumor suppressor, facilitated by TXNIP’s ability to inhibit glucose uptake and aerobic glycolysis." (PMID 40175348, 2025). "In summary, our study confirmed the inhibitory effect of COR on HCC, and, for the first time, we showed that COR achieved this effect by increasing TXNIP-induced tumor cell pyroptosis." (PMID 40008893, 2025).
tumor (continued). "We also observed a decrease of TXNIP protein along tumor progression, correlating with Gleason score, similarly to what was observed in the TRAMP model." (PMID 41213907, 2025). "Our results in a cohort of patients indicate that TXNIP protein levels are higher in healthy tissue compared with tumor tissue from the same individual." (PMID 41213907, 2025). "In the multivariate Cox proportional hazards model, low TXNIP expression, poor tumor differentiation, and microvascular invasion were independent prognostic indicators of OS." (PMID 40008893, 2025). "To further validate the functional activity of TXNIP removal in primary human T cells, we assessed the effect of TXNIP KO in T cells on tumor growth in vitro by performing an antigen specific T cell killing assay." (PMID 40260243, 2025). "Several reports have demonstrated that increases in TXN and TXNRD1 under glucose deprivation conditions support cancer cell survival and migration 62, 63, whereas enhanced stability of TXNIP mRNA inhibits tumor metastasis and glycolysis." (PMID 39744566, 2025). "Conversely, TXNIP is underexpressed in most cancer cells, and there is convincing evidence showing its levels are inversely correlated with tumor progression." (PMID 40558539, 2025). "Initially described as a tumor-suppressor gene, some studies showed a pro-tumoral effect of TXNIP expression." (PMID 40260243, 2025). "In this paper, TXN, TXNRD1 and TXNIP are integrated for the first time to comprehensively analyze the importance and indication of the Trx system in tumor and immunotherapy." (PMID 39744566, 2025). "In parallel, patients’ data were analyzed and showed that TXNIP is highly expressed in T lymphocytes and that its expression is reduced in tumor-infiltrating CD4+ T cells compared to those in paired normal adjacent tissue and blood." (PMID 40260243, 2025). "Based on our previous study showing that TXNIP activation by UNC0642 suppressed cell proliferation and tumor growth, we conducted TXNIP knockdown or overexpression in BC cells to investigate the direct impact of TXNIP on BC cell growth and survival." (PMID 40175348, 2025). "In other cell types (murin hepatocytes or tumor cells) PI3K/Akt signaling has been shown to directly inhibit TXNIP." (PMID 40260243, 2025). "Previous in vitro cell experiments have demonstrated that NCL regulates the anti-tumor immune function of CD8 + T cells via targeting the MYC/TXNIP axis." (PMID 40346484, 2025). "Using the CPTAC database, we verified that TXN, TXNRD1 and TXNIP proteins were also aberrantly expressed in the tumor." (PMID 39744566, 2025). "Increased cellular amounts of TXNIP results in oxidative stress, accumulation of DNA damage and increased apoptosis in tumor cells." (PMID 39364720, 2025). "While TXNIP and IL-24 act as tumor suppressors, STAT3 is considered an oncogene, being constitutively activated in nearly 70% of solid and hematological tumors." (PMID 40175348, 2025). "Using TCGA datasets, we then explore the mRNA levels of TXN, TXNRD1, and TXNIP in tumor and adjacent normal tissues and found similar results." (PMID 39744566, 2025). "The high expression of TXN and TXNRD1, as well as the low expression of TXNIP group exhibited lower levels of tumor immune infiltration." (PMID 39744566, 2025). "TXNIP is crucial for the maturation of NK cells and the function of DCs in the tumor microenvironment, thus influencing anti-tumor immunity." (PMID 40182050, 2025). "Our analysis highlighted that, in lymphocytes, TXNIP expression was reduced in activated T cells as well as in tumor compared to paired blood and normal tissues." (PMID 40260243, 2025). "In vivo, TOB1‐AS1 overexpression significantly inhibited tumor growth and altered miR‐27a‐3p and TXNIP expression profiles." (PMID 40665897, 2025). "Expression of TXNIP and TXN was examined in histological slides of 6 ESRD and 6 ACRD kidneys, precursor lesions and associated tumours as well as of RCCs from the general population by immunohistochemistry." (PMID 39020292, 2024).